AKAP1 (A-kinase anchoring protein 1)
Diseases named in the same sentence as AKAP1 in open-access papers (continued):
Sharing a sentence is not in itself a finding about the gene and the disease.
schizophrenia (3 papers, 2011 to 2024). A major psychotic disorder characterized by abnormalities in the perception or expression of reality. "These genes included SBNO2, CEACAM5, AKAP1, UBC, ACTB, UBB, and FOS for schizophrenia; SEC24C, PGLYRP1, ARHGAP4, RPL22, SLC6A11, and SYK for bipolar disorder; and SRRT, PARK2, LILRA4, STK17A, IGFBP2, and NF1 for major depression." (PMID 22373040, 2011). "Besides, PDE4A was related to heat shock protein B6 (HSPB6), aldehyde dehydrogenase 7A1 (ALDH7A1), A-kinase anchoring protein 1 (AKAP1), adrenoceptor beta 2 (ADRB2), SAG (an arrestin family member which desensitizes GPCR) and DISC1 (disrupted in Schizophrenia 1)." (PMID 38514754, 2024).
Stroke (3 papers, 2019 to 2022). Sudden impairment of blood flow to a part of the brain due to occlusion or rupture of an artery to the brain. "A 2018 study shows that the loss of AKAP1 promoted mitochondrial fission due to reduced Drp1 phosphorylation at Ser637, localized Drp1 to the brain mitochondria and exacerbated stroke in a murine model of transient cerebral ischemia." (PMID 36263130, 2022). "Since we know AKAP1 KO mice are more sensitive to stroke, future studies on changes occurring in the neurocircuitry in the AKAP1 KO mice, and perhaps the resulted changes learning and memory on the behavioral level will be very interesting in terms of exploring novel roles of AKAP1." (PMID 31991888, 2020). "In a recent report from our laboratory, these findings were extended in vivo when mice lacking AKAP1 were shown to have increased sensitivity to stroke injury." (PMID 31991888, 2020).
Cognitive impairment (2 papers, 2024). Abnormal cognition is characterized by deficits in thinking, reasoning, or remembering. "LIG alleviates mitochondrial dysfunctions and cognitive impairment via the PKA/AKAP1 signaling pathway." (PMID 37718506, 2024). "Moreover, this cognitive impairment was rescued in a gene dose-dependent manner by deletion of the Drp1 inhibitor PKA/Akap1." (PMID 38659734, 2024).
lung carcinoma (2 papers, 2017 to 2024). "Conversely, disparate findings emerge from studies on human cancer cells and tissue samples, where AKAP1 is notably overexpressed, including in breast, prostate, and lung cancer tissues." (PMID 39118833, 2024). "In lung cancer, AKAP1 expression correlates with high levels of Myc, mTOR phosphorylation and reduced patient survival." (PMID 28569781, 2017).
Myocardial fibrosis (2 papers, 2016 to 2023). "Interestingly, 3MA treatment reduced apoptotic cell death in Akap1-/- mice after MI, and although it increased myocardial fibrosis in the same group, it significantly improved cardiac dysfunction in Akap1-/- mice one week after MI, as shown by a significant increase in % fractional shortening." (PMID 27136357, 2016).
non-small cell lung carcinoma (2 papers, 2017 to 2025). A group of at least three distinct histological types of lung cancer, including non-small cell squamous cell carcinoma, adenocarcinoma, and large cell carcinoma. "A validated tissue microarray (TMA) containing tumor samples derived from patients that underwent to surgery for non-small cell lung cancer (NSCLC) was subjected to immunostaining analysis for AKAP1." (PMID 28569781, 2017).
Parkinson disease (2 papers, 2011 to 2020). A progressive degenerative disorder of the central nervous system characterized by loss of dopamine producing neurons in the substantia nigra and the presence of Lewy bodies in the substantia nigra and locus coeruleus. "We expressed AKAP1-GFP in hippocampal neurons andscored apoptosis either under basal conditions or 2 d after treatment withrotenone, an inhibitor of complex 1 of the electron transport chain that iscommonly used as a chemical model of Parkinson's disease." (PMID 21526220, 2011).
transient cerebral ischemia (2 papers, 2020 to 2022). "Emerging evidence showed that mice lacking AKAP1 exhibit increased infarct size following transient cerebral ischemia as well as increased Drp1 localization to mitochondria from the forebrain tissues and decreased Drp1 phosphorylation at Ser63724." (PMID 32312949, 2020).
asthma (1 paper, 2022). "The gene AKAP1, mapped to cg02467794, showing consistent and statistically significant interaction effects in both cohorts in females, has been shown to be associated with asthma in the Agricultural Lung Health Study." (PMID 35207690, 2022). "Genes that the identified CpGs were mapped to, e.g., AKAP1 and ENO1, have been shown to be associated with the risk of asthma." (PMID 35207690, 2022).
Bardet-Biedl syndrome (1 paper, 2008). A ciliopathy with multisystem involvement. "For example, the gene pair containing Akap1 (A kinase anchor protein 1), and Bbs9 (Bardet-Biedl syndrome 9) using Lin and Jiang methods score a similarity of 1.0." (PMID 18680592, 2008).
Breast Invasive Carcinoma (1 paper, 2018). "Interestingly, AKAP1 amplifications was the most frequent mutation in the Breast Invasive Carcinoma TCGA data set altered in 8% of the tumors (n = 1098), data from cbioportal.org." (PMID 29433456, 2018).
cardiac arrest (1 paper, 2017). Cessation of breathing and/or cardiac function. "Thus, the AKAP1/PKA complex system may be involved in regulation of balance in mitochondrial fission and fusion and protection from brain injury after cardiac arrest." (PMID 29445732, 2017).
cerebrovascular diseases (1 paper, 2018). "The absence of Akap1 has been variously associated with increased ROS production and mitochondrial dysfunction in several models of cardio- and cerebrovascular diseases as well as in cancer." (PMID 29892230, 2018).
colorectal cancer (1 paper, 2018). A primary or metastatic malignant neoplasm that affects the colon or rectum. "AKAP1 was shown to be required for cAMP-dependent PKA mediated apoptosis in colorectal cancer cells upon IGF1R inhibition." (PMID 29433456, 2018).
fibrosis (1 paper, 2016). the formation of excess fibrous connective tissue in an organ or tissue in a reparative or reactive process. "One week after MI, cardiac function and survival were also significantly reduced in Akap1-/- mice, while cardiac fibrosis was significantly increased." (PMID 27136357, 2016).
Hyperglycemia (1 paper, 2024). An increased concentration of glucose in the blood. "Streptozotocin (STZ)-induced hyperglycemia in rats enhances Drp1 phosphorylation at Ser637 and its recruitment to AKAP1." (PMID 39273390, 2024). "Streptozotocin (STZ)-induced hyperglycemia in rats enhances Drp1 phosphorylation at Ser637 and recruitment to AKAP1." (PMID 39273390, 2024).
lung injury (1 paper, 2022). "In light of our current findings, AKAP1 overexpression and modulation of Drp1 phosphorylation at Ser637 is an important therapeutic strategy for acute lung injury." (PMID 36263130, 2022).
neuroblastoma (1 paper, 2017). Neuroblastoma (NB) is the most common solid, extracranial childhood tumor. "To this end, we monitored the relative levels of AKAP1 protein and RNA in the human Tet-21/N neuroblastoma cell line conditionally expressing MYCN under the control of a Tet-Off (tetracycline) promoter." (PMID 28569781, 2017). "First, we determined if MYCN regulates AKAP1 expression in neuroblastoma cells, where MYCN is critical to oncogenesis." (PMID 28569781, 2017).
prostate adenocarcinoma (1 paper, 2021). "In contrast, in prostate adenocarcinoma tissues, UCP2 expression is reduced, while several MAM-stabilizing proteins, including AKAP1, RICTOR, GPR75, and PEMT1, were found to be upregulated." (PMID 33614647, 2021).
sarcoma (1 paper, 2024). A usually aggressive malignant neoplasm of the soft tissue or bone. "For this we selected three RBPs which are among the top 20% most elevated in the sarcoma interactomes: IGF2BP3, MEX3A and AKAP1." (PMID 38561347, 2024).
cancer (25 papers, 2012 to 2025). A tumor composed of atypical neoplastic, often pleomorphic cells that invade other tissues. "Several studies from other groups published in recent years have also shown higher AKAP1 expression is associated with poor prognosis in different human cancers." (PMID 31991888, 2020). "In summary, when evaluating the potential of using AKAP1 as a diagnostic biomarker or drug target for cancer treatment, the heterogeneity of cancer cell population needs to be taken into serious consideration." (PMID 31991888, 2020). "The decreased AKAP1 level is thought to be associated with metabolic reprogramming from oxidative phosphorylation to glycolysis as the cancer cell required faster energy production." (PMID 31991888, 2020). "AKAP1 is highly expressed in various human cancers and facilitates the metabolic adaptation of cancer cells by upregulating oxidative phosphorylation." (PMID 40876456, 2025). "According to some studies, an increase in Akap1 has been detected in cancer patients, with studies demonstrating that Akap1, which is a target of proto-oncogene, Myc, stimulates the mTOR pathway, resulting in the development of cancer." (PMID 38918814, 2024). "Akap1−/− mice are a valuable tool to dissect the role of AKAP1 in cardiovascular, neurodegenerative diseases and cancer." (PMID 36263130, 2022). "Several recent studies have suggested that the role of AKAP1 in cancer is complicated due to the heterogeneous nature of cancer cells in different stages of tumor growth and metastasis." (PMID 31991888, 2020). "We focus on the recent literature on AKAP1′s roles in metabolic homeostasis, cancer and cardiovascular and neurodegenerative diseases." (PMID 31991888, 2020). "In cancer, the expression level of AKAP1 seemed to be closely correlated with the metabolic program adopted by different types of cancer cell." (PMID 31991888, 2020). "On the other hand, increased AKAP1 expression is observed in tumors of end-stage cancer patients as well as in cisplatin chemotherapy resistance." (PMID 31991888, 2020). "While one study suggested AKAP1 inhibits cancer cell invasiveness, other studies have reported a poorer prognosis with higher AKAP1 expression." (PMID 31991888, 2020). "Future studies will be of interest in understanding the differential regulation of AKAP1 in cancer pathogenesis." (PMID 31991888, 2020). "Here, we provide evidence that AKAP1 is a transcriptional target of Myc and supports the growth of cancer cells." (PMID 28569781, 2017). "In this context, high levels of AKAP1 were detected in wide array of human cancer cells and tissues, suggesting a role of this protein in the metabolic processes of actively proliferating cells." (PMID 28569781, 2017). "Collectively, these data disclose a previously unrecognized role of AKAP1 in mTOR pathway regulation and cancer growth." (PMID 28569781, 2017). "Transcriptional regulation of AKAP1 by Myc would provide an energetic advantage to cancer cells, enhancing energetic metabolism and the anabolic pathway." (PMID 28569781, 2017). "Here, we report that mitochondrial AKAP1 is a novel transcriptional target of Myc which controls the mTOR pathway and cancer cell growth." (PMID 28569781, 2017). "We provide evidence that mitochondrial AKAP1 is a novel Myc transcriptional target and is highly expressed in a wide array of human cancer tissues." (PMID 28569781, 2017). "The complex assembled by AKAP1 on mitochondria is particularly relevant for cancer cells, as it provides sufficient energy for the synthesis of the building blocks of cellular organelles." (PMID 28569781, 2017). "Six additional non-synonymous SNVs were discovered and confirmed, including variants in AKAP1, PCNT and RERE, all of which have been implicated in cancer." (PMID 23803469, 2013). "However, limited research exists in animal models investigating how cancer occurs when the Akap1 expression is enhanced." (PMID 38918814, 2024).
cancer (continued). "AKAP1 is a transcriptional target of Myc and supports the growth of cancer cells." (PMID 36899892, 2023). "AKAP1 involves in mTOR pathway regulation and cancer growth." (PMID 36672755, 2022). "Clearly, a more precise understanding of how AKAP1 modulates mitochondrial function in responding to upstream cellular signaling can help us better understand the metabolic reprogramming process of the cancer cells." (PMID 31991888, 2020). "In addition, we discuss the unique involvement of AKAP1 in cancer tumor growth, metastasis and resistance to chemotherapy." (PMID 31991888, 2020). "Moreover, since AKAP1 is pro-survival, its elevation protects the cancer cells from cisplatin, presumably aiding in the development of chemotherapy resistance." (PMID 31991888, 2020). "For example, high levels of AKAP1 were found in variety of high-grade cancer tissues." (PMID 31442208, 2019). "Recently, Akap1 has been shown to control mTOR regulating cancer cells growth." (PMID 29892230, 2018). "We therefore monitored the levels of AKAP1 in different human cancer cells and tissue samples." (PMID 28569781, 2017). "High levels of AKAP1 were found in a wide variety of high-grade cancer tissues." (PMID 28569781, 2017). "Since Myc is often up-regulated in human tumors, we suspected that AKAP1 might also be highly expressed in cancer." (PMID 28569781, 2017). "Interfering with the signaling events regulated by AKAP1 at mitochondria and modulating its interaction with components of the metabolic pathways could provide novel molecular targets for cancer therapy." (PMID 28569781, 2017). "While this study may appear to be contradictory to studies where increased AKAP1 has been viewed as a “bad” sign for cancer patients, a closer look opens up very fascinating discussions about the dynamic changes adopted by cancer cells when transitioning at different disease stages." (PMID 31991888, 2020). "AKAP1/mTOR signal integration on mitochondria may provide a new target for cancer therapy." (PMID 28569781, 2017). "Thus, genetic silencing of AKAP1 severely impaired oxidative metabolism and growth of cancer cells." (PMID 28569781, 2017). "Notably, expression levels of proteins facilitating mitochondrial-ER interaction, including AKAP1, RICTOR, Rab32, PACS2, GPR75, and PEMT1, were reduced in these cancer tissues." (PMID 33614647, 2021). "In summary, we can perhaps picture the following scenario for cancer progression: at the tumor stroma, the cells metabolically favor glycolysis and fuel the epithelial cancer cells, which adopt high OXPHOS cellular respiration (high AKAP1) to promote tumor growth." (PMID 31991888, 2020). "Also, many targeted genes, such as ZEB1, SOX5, AKAP1, CHP1, CNBP, VEGFR, and MAGT1, play a vital function in the cell shape, movement, invasion, adhesion, and polarity formation, so as to involve in many kinds of diseases such as malignant tumors, wound healing, and so on." (PMID 32547593, 2020).
tumor (16 papers, 2011 to 2024). "AKAP1 expression is associated with APOC1 overexpression, promotes tumor progression, and has a poorer prognosis for patient survival." (PMID 36591507, 2022). "Given its positive role in mTOR pathway and tumor growth, we investigated the expression profile of AKAP1 and its correlation with myc and mTOR in human tumor tissues." (PMID 28569781, 2017). "AKAP1 may contribute to tumor progression and result in poor overall and disease-free survival rates in patients with HCC." (PMID 34917619, 2021). "AKAP1 is required for tumor cell growth in vitro and in vivo." (PMID 28569781, 2017). "Downregulation of AKAP1-reduced tumor weight by about 2.5-fold." (PMID 28569781, 2017). "It has been proved that AKAP1, SNAI1 and Caprin1 could be target genes of miR-199a-5p, and their overexpression worsens tumor developments." (PMID 35517408, 2022).
cardiovascular disease (6 papers, 2018 to 2025). "In cardiovascular diseases, hyperoxia-induced lung injury and ischemia-induced neurodegeneration, AKAP1 has been shown to support cell survival." (PMID 31991888, 2020).
infection (2 papers, 2016 to 2022). The state of being infected such as from the introduction of a foreign agent such as serum, vaccine, antigenic substance or organism. "The differentially expressed proteins post-infection include Akap1, Prkaca, Prkab2, Acaca, Acacb, Aka1, Abcf1, Synj1, Braf, Vcl, and Fhod3, which involve insulin receptor signal, glucagon signal pathway, AMPK signal pathway, and Hippo signal pathway." (PMID 35313969, 2022).
adenocarcinoma (1 paper, 2017). A common cancer characterized by the presence of malignant glandular cells. "Most cases with high/moderate levels of AKAP1 staining were adenocarcinoma (47/87) and the statistical analysis showed a significance association between AKAP1 expression and adenocarcinoma histotype (P=0.004)." (PMID 28569781, 2017).
bacterial infection (1 paper, 2022). "We identified five genes—S100PBP, AKAP1, USP6NL, CDON and SULF2—in five different patient subgroups that have been associated with viral and/or bacterial infection in the literature." (PMID 36517845, 2022).
AKAP1 also shares sentences with these, for which no sentence is quoted: neurodegenerative disease (4 papers); Alzheimer disease (3); Insulin resistance (3); bipolar disorder (2); chronic heart failure (2); depression (2); dyslipidemia (2); metabolic disease (2); Anxiety (1); Arrhythmia (1); atherosclerosis (1); atrial fibrillation (1); atypical hemolytic-uremic syndrome (1); autism (1); Azoospermia (1); brain ischemia (1); colon cancer (1); cryptorchidism (1); Cushing syndrome (1); diffuse large B-cell lymphoma (1); dilated cardiomyopathy (1); endocrine disorders (1); endothelial dysfunction (1); glioma (1); heart disease (1); Hypertension (1); immune deficiencies (1); infarct (1); ischemic stroke (1); left ventricular hypertrophy (1).
A further 12 diseases each share a sentence with AKAP1 in 1 paper.